FGF21 (fibroblast growth factor 21)
Diseases named in the same sentence as FGF21 in open-access papers (continued):
Sharing a sentence is not in itself a finding about the gene and the disease.
metabolic disease (continued). "Future studies will be conducted on several novel aspects, such as the central metabolic effects of FGF-21 and the effects of FGF-21 on non-metabolic diseases." (PMID 36238554, 2022). "Fibroblast growth factor 21 (FGF21), which is mainly synthesized and secreted by the liver, plays a crucial role in systemic glucose and lipid metabolism, ameliorating metabolic diseases." (PMID 36235573, 2022). "An important next step will be to determine whether elevations in FGF21 are coupled to specific changes in FGF21 receptors or to factors binding to the receptors that render it less efficacious following repeated stimulation, and how it can be best targeted to treat metabolic diseases." (PMID 34141520, 2021). "Current studies on the endocrine FGF family have demonstrated the importance of FGF19, FGF21, and FGF23 in human genetic and metabolic disorders, suggesting their therapeutic role in metabolic diseases." (PMID 34572066, 2021). "The activation of PPARγ also induces the expression of fibroblast growth factor 21 (FGF21), which has been shown to improve metabolic disorders in humans and mice." (PMID 34943840, 2021). "Fibroblast growth factor 21 (FGF21), is an emerging metabolic regulator mediates multiple beneficial effects in the treatment of metabolic disorders and related complications." (PMID 34349728, 2021). "These same inflammatory pathways are suppressed in vivo upon FGF21 administration in animal models of NASH and other metabolic diseases." (PMID 33381084, 2020). "FGF21 and its analogs have demonstrated consistent anti-fibrotic effects in cell culture systems and animal models of NASH, liver injury, or metabolic disease." (PMID 33381084, 2020). "Recent attention in the search for novel therapies has focused on fibroblast growth factor 21 (FGF21), a pleotropic metabolic regulator which has several potential applications in the treatment of metabolic disease." (PMID 26635356, 2016). "Serum FGF21 levels are also increased with NAFLD, metabolic disorders, and types 2 diabetes as well as CAD." (PMID 27803896, 2016). "One of the most recently identified mediators that facilitates organ cross talk and the related control of impaired glucose homeostasis in metabolic diseases is a member of the FGF family, FGF-21." (PMID 23861559, 2013). "FGF21 and GDF15 act synergistically to maintain glucose homeostasis and promote resistance to DIO in mice lacking OPA1 in BAT, highlighting the potential of combined therapies using FGF21 and GDF15 for the treatment of metabolic disorders." (PMID 40897647, 2025). "Additionally, the interaction between FGF21 and PPARGC1A pathways is crucial for understanding metabolic disorders." (PMID 41465464, 2025). "One gene therapy strategy involves using an AAV-FGF21 vector to enhance the interaction between the fibroblastic growth factor FGF21 and its coreceptor β-klotho, thereby activating the ERK1/2 and MAPK signaling pathways to address metabolic diseases." (PMID 40006994, 2025). "Fibroblast growth factor 21 (FGF21) is a nonclassical fibroblast growth factor that also plays a role in the treatment of metabolic disorders." (PMID 38644407, 2024). "Activation of elements within the FGF21/AMPK/PGC-1α cascade is crucial in regulating mitochondrial energy metabolism and has attracted considerable attention as a potential therapeutic target for addressing metabolic disorders like NAFLD." (PMID 39161898, 2024). "The levels of serum FGF-21 in patients with FP, as a common metabolic disease, have not been reported." (PMID 37070097, 2023). "Currently, the development of FGF21 analogues or mimics through biopharmaceutical engineering approaches also greatly enriches the possibility of FGF21 as a therapeutic target for metabolic diseases, such as the clinical trials of LY2405319 and PF-05231023 in metabolic diseases are under way." (PMID 37576954, 2023).
metabolic disease (continued). "Better understanding of the roles of endogenous FGF21 and GDF15 in health and disease might lead to the development of new therapies to treat metabolic disorders." (PMID 37818094, 2023). "The soy protein β-conglycinin is a good example of an ATF4 activator that can prevent metabolic disorders through the induction of FGF21 without ER stress." (PMID 35159314, 2022). "Studies with rodent models have shown that fibroblast growth factor 21 (FGF21) is a metabolic regulator induced in the liver in response to different stress conditions, such as energy and nutrient deprivation, inflammation, and metabolic disorders." (PMID 36611740, 2022). "FGF21 directly stimulates the secretion of adiponectin and corticosteroids through FGFR1/β-klotho signaling or indirectly activates AMPK signaling to control metabolic disorders and the aging process." (PMID 36267567, 2022). "A cross-sectional study in a Chinese population unmasked that serum FGF21 levels in CAD patients increased with the severity of metabolic disorders, independent of age, gender and BMI." (PMID 35909513, 2022). "Numerous studies using recombinant FGF21 proteins, FGFR-activating antibodies or long-acting FGF21 analogues have been performed to evaluate the relevance of such therapies to treat metabolic disorders in classical animal models, leading to promising results and no serious deleterious side effects." (PMID 35409319, 2022). "It is possible to speculate that the level of FGF21 is adaptively increased in the early stages of CKD, which contributes to alleviate the metabolic disorders." (PMID 34675822, 2021). "There are few or no studies involving FGF21 for the treatment of aging-related metabolic diseases by improving aging." (PMID 33869312, 2021). "Fibroblast growth factor 21 (FGF21) is a peptide hormone mainly secreted by the liver and brown adipose tissue, with potential clinical utility as a therapeutic approach for metabolic diseases due to its enhancement of insulin sensitivity and weight loss." (PMID 32188054, 2020). "Individuals with metabolic disease may have higher circulating FGF21 levels but may also have higher levels of FAP and therefore less intact circulating FGF21, which may in turn contribute to dysmetabolism." (PMID 31687174, 2019). "Given the disease-related changes in levels of relevant cytokines (for instance, leptin, adiponectin, reisitin, FGF21, Fetuin A, TNF-α, IL-6, MCP-1), these factors may serve as biomarkers for the early detection of metabolic disorders." (PMID 31736870, 2019). "Moreover, based on preclinical studies, certain cytokines (FGF21, leptin, adiponectin, irisin) that can induce improvements in glucose and lipid metabolism and may emerge as novel targets of broader and more efficacious treatments and prevention of metabolic disease." (PMID 31736870, 2019). "Moreover, visceral adipose tissue, a type of fat targeted by FGF21 that is especially sensitive to metabolic disease‐associated alterations, and liver, could not be studied for the obvious reasons that such biopsies cannot ethically be obtained from aged healthy volunteers." (PMID 30043445, 2018). "Although the fibroblast growth factor-21 (FGF-21) and irisin roles are well demonstrated in metabolic disease, there have been no reports investigating the effect of resistance exercise on FGF-21 and irisin levels in diabetic skeletal muscles." (PMID 29036766, 2017). "From recent studies, fibroblast growth factor-21 (FGF-21) and irisin have been known to be peroxisome proliferator-activated receptor gamma coactivator 1-alpha (PGC-1 alpha)-related potential therapeutic targets for metabolic diseases." (PMID 29036766, 2017). "Although the roles of FGF-21 and irisin have been well demonstrated in metabolic disease, there has been no report to investigate the effect of resistance exercise on FGF-21 and irisin levels in diabetic skeletal muscles." (PMID 29036766, 2017).
metabolic disease (continued). "Although study subjects were healthy population which are not presenting any signs of metabolic disorder, serum levels of FGF-21 were upregulated by smoking." (PMID 26382974, 2015). "In addition, FGF1, FGF10, and FGF21 have been shown to be adipokines with crucial roles in WAT or BAT functions, suggesting new roles for FGFs and potential therapeutic strategies for metabolic disorders." (PMID 24605108, 2014). "Human recombinant wild type FGF21 (FGF21) has been shown to ameliorate metabolic disorders in rodents and non-human primates." (PMID 23536797, 2013). "If our assumption turned out to be true, then a decrease of FGF21 level in NAFLD patient might indicate a decompensatory stage of the disease and might accompany with an acute deterioration of a series of metabolic disorders." (PMID 21949781, 2011). "Beyond regulating metabolic disorders in T2D, FGF21 may also directly act on the heart to ameliorate DCM, as FGFR1 and KLB—the receptor and co-receptor mediating the biological functions of FGF21—are expressed in cardiac tissue)." (PMID 40724827, 2025). "Therefore, modulation of FGF21 signaling pathway could emerge as a target in IBD and related metabolic disorders." (PMID 38983722, 2024). "FGF21, belonging to of the fibroblast growth factor (FGF) family and initially discovered in the liver, shares approximately 75% amino acid sequence similarity between mice and humans, demonstrating potential therapeutic benefits in addressing metabolic disorders in preclinical studies." (PMID 39221030, 2024). "In addition, FGF21 resistance is observed in metabolic diseases including NAFLD, suggesting that aberrant expression in these scenarios may endow FGF21 with aberrant activities, such as the tumor-promoting effect observed in our study." (PMID 38238320, 2024). "It is not clear whether there is “FGF-21 resistance” in populations with metabolic diseases, which requires further study." (PMID 37070097, 2023). "There is some evidence indicating that the elevated FGF-21 levels may not be the primary mechanism through which omega-3 PUFAs alleviate metabolic disorders." (PMID 38035345, 2023). "The physiological roles, clinical translation, and FGF-21-based drug development were the main topics of research, and future studies may concentrate on the central effects of FGF-21, FGF-21-based drug development, and the effects of FGF-21 on non-metabolic diseases." (PMID 36238554, 2022). "Another study exhibited that lack of FGF21 could worsen the metabolic disorders in NASH and provide the microenvironment, wherein inflammation, regenerating proliferation of hepatocytes and fibrosis may happen." (PMID 36457562, 2022). "In addition to FGF21 analogs, the FGFR1/β-klotho complex (FGF21 receptor agonists, FGF21RAs) opened a new door for aging-associated metabolic diseases, which have been tested in non-human primates (NHPs) and humans." (PMID 33869312, 2021). "However, by strictly matching body mass indices, serum FGF21 levels correlate in patients with metabolic disorders, but not CAD, indicating that this relationship is attributed more to preexisting cardio-metabolic factors than CAD per se." (PMID 27803896, 2016). "To date, the physiological significance for increased FGF21 in metabolic disease is not elucidated." (PMID 24260557, 2013). "Moreover, prospective studies of HT patients without concomitant cardiovascular or metabolic disorders could reveal the potential role of FGF21 in the development of cardiovascular events or metabolic abnormalities." (PMID 39452947, 2024). "FGF21 knockout mice showed cardiac dysfunction, accompanied by a decline in global longitudinal strain (GLS) and ejection fraction (EF), independent of metabolic disorders." (PMID 37156793, 2023). "Secondly, the markedly abnormal serum FGF-21 levels seen in some patients with no significant COX defect suggest a non-mitochondrial origin, as has been observed in other metabolic disorders." (PMID 24252301, 2013).
metabolic disease (continued). "However, there have been no clinical trials about the application of FGF21-based drugs in CVD treatment, and most clinical trials have investigated the application of FGF21 in metabolic diseases." (PMID 36594101, 2023). "Our current finding is consistent with the results of the previous FGF21 study, suggesting that ISR signaling may be improving whole-body metabolism of metabolic disorder in a non-cell-autonomous manner." (PMID 34877504, 2021).
cardiovascular diseases (95 papers, 2010 to 2025). "A series of clinical trials and meta-analyses reported that elevated serum FGF21 levels were associated with an increased incidence of cardiovascular diseases (CVD) as well as cardiovascular mortality among patients with diabetes." (PMID 36926038, 2023). "Previous studies have not only demonstrated an association between cardiorespiratory fitness and serum FGF21 but also that FGF21 is predictive of future adverse cardiovascular disease events." (PMID 36986211, 2023). "Considering the close association between metabolic syndrome and cardiovascular disease, an increasing number of studies have investigated the beneficial effects of FGF21 on the cardiovascular system." (PMID 36926038, 2023). "And it was reported that elevated circulating levels of FGF21 were associated with cardiovascular disease (CVD)." (PMID 36618930, 2022). "FGF21 improved the lipid profiles and increased the adiponectin levels in diabetic and obese subjects who were predisposed to cardiovascular disease (CVDs)." (PMID 32227589, 2020). "Clinical and preclinical studies have demonstrated that patients with cardiovascular diseases (CVDs) are always closely associated with serum FGF21 increase." (PMID 29445083, 2018). "FGF21 was significantly associated with cardiovascular disease (HR 1.12 [95% CI 1.03–1.12])." (PMID 40356318, 2025). "With a decrease in vitamin D level, there are an increase in FGF-21 level, a reduction in adiponectin level, high oxidative stress, and inflammation in these subjects that may predispose them to increased cardiovascular disease risk." (PMID 39544568, 2024). "However, the studies on the association of circulating FGF21 levels with cardiovascular disease (CVD) or MACEs are inconsistent." (PMID 37724523, 2023). "Similar to our study, elevated FGF21 is associated with poor prognosis in cardiovascular disease." (PMID 35369322, 2022). "However, despite as a biomarker and diagnostic indicator of DM-related cardiovascular diseases in clinic, the clinical implementation of FGF21 still has some obstacles due to its complex pharmacokinetic and biophysical characteristics." (PMID 34349728, 2021). "Importantly, triglyceride lowering and a beneficial shift in plasma lipoprotein profiles suggest the potential of an FGF21-based therapy for amelioration of cardiovascular disease risk." (PMID 23536797, 2013). "Because FGF-21 is an adipokine with glucose-lowering effects, it was speculated that the paradoxical increase of this protein in populations with risk of cardiovascular disease is a compensatory mechanism to counteract metabolic stress." (PMID 21206918, 2010). "Therapeutic strategies for cardiovascular diseases based on FGF21 primarily revolve around its pleiotropic metabolic regulatory functions." (PMID 41234361, 2025). "Due to the effects of FGF21 analogs on parameters such as blood pressure and heart rate, current research in cardiovascular diseases remains largely confined to the preclinical stage." (PMID 41234361, 2025). "FGF21 potentially serves as a novel target for the prediction and treatment of cardiovascular diseases." (PMID 38333506, 2024). "The reduced expression of FGF21, a cardiac kinin released under pathological stress, along with its co-receptor β-Klotho, can lead to FGF21 resistance and exacerbate the compensatory response to cardiovascular disease." (PMID 39308872, 2024). "There is growing evidence that the administration of exogenous FGF21 generally provides a protective impact on cardiovascular disease." (PMID 39335666, 2024). "This cardioprotective and prognostic prediction of cardiovascular disease by FGF21 is similar to that of BNP." (PMID 36778154, 2023). "Although a protective role of FGF21 in cardiac function and metabolism has been found, the link between FGF21 and cardiovascular disease is controversial." (PMID 36926038, 2023).